HIF1A (hypoxia inducible factor 1 subunit alpha)
Diseases named in the same sentence as HIF1A in open-access papers (continued):
Sharing a sentence is not in itself a finding about the gene and the disease.
renal adenocarcinoma (1 paper, 2019). "MVP can also promote the degradation of HIF1α, a known tumor promoting factor, and function as a tumor suppressor in renal adenocarcinoma cells." (PMID 31092229, 2019).
Renal Oncocytoma (1 paper, 2019). "This is due to the inability of the tumor to stabilize HIF1α following the occurrence of pathogenic mitochondrial DNA (mtDNA) mutations, a distinctive hallmark of renal oncocytoma." (PMID 30728892, 2019). "Hence, we stained the renal oncocytoma for the hydroxylated form of HIF1α with the aim to understand whether the HIF1α positivity we observed was indeed due to the inactive form of the transcription factor, unable to be degraded in a VHL-deficient context." (PMID 30728892, 2019).
renovascular hypertension (1 paper, 2023). High blood pressure secondary to renal artery stenosis. "In this study of 2K1C renovascular hypertension HIF-1α stabilization was found in some tubular epithelial cells mainly of the kidney medulla using immunohistochemistry." (PMID 37435301, 2023).
respiratory depression (1 paper, 2024). A decrease in ventilation secondary to impaired signals from the central nervous system. "Simultaneously, the elevated levels of NO induce mitochondrial dysfunction and inhibit cellular respiration, resulting in a reversal of tumor hypoxia and a downregulation of HIF-1α expression, which is typically upregulated due to oxygen conservation associated with respiratory depression." (PMID 39659580, 2024).
respiratory failure (1 paper, 2025). The significant impairment of gas exchange within the lungs resulting in hypoxia, hypercarbia, or both, to the extent that organ tissue perfusion is severely compromised. "Hypoxia secondary to respiratory failure also compromises blood–brain barrier (BBB) function by inducing vascular endothelial growth factor (VEGF) signaling, oxidative stress, and hypoxia-inducible factor 1-alpha (HIF-1α)-dependent modulation of ACE2." (PMID 40507911, 2025).
respiratory syncytial virus infection (1 paper, 2025). "During influenza A virus (IAV) and respiratory syncytial virus infection (RSV), elevated ROS levels activate HIF-1α-mediated glycolytic pathway to compensate for the energy deficit, contributing the replication." (PMID 40691814, 2025).
Retinal dysplasia (1 paper, 2017). Abnormal growth and differentiation, structure and appearance of the retina present from birth. "Pathway analyses suggested a decrease in cellular respiration and increased expression of components of Hif1-α, VEGF, mTOR, NFκβ, and multiple interleukin pathways are associated with early retinal dysplasia." (PMID 28192065, 2017).
retinal hemangioblastoma (1 paper, 2015). A hemangioblastoma that arises from the retina. "Further, HIF-1α expression was increased within the retinal hemangioblastoma, which is consistent with previous findings that there are many HIF transcripts in retinal hemangioblastomas." (PMID 25885645, 2015).
retinitis pigmentosa (1 paper, 2021). Retinitis pigmentosa (RP) is an inherited retinal dystrophy leading to progressive loss of the photoreceptors and retinal pigment epithelium and resulting in blindness usually after several decades. "Effect of dominant negative HIF1α and Best1-Txnip.C247S.LL351 and 352AA on retinitis pigmentosa cone survival." (PMID 33847261, 2021).
Rett syndrome (1 paper, 2023). A severe neurodevelopmental disorder affecting the central nervous system.
rhabdomyolysis (1 paper, 2022). Necrosis or disintegration of skeletal muscle often followed by myoglobinuria. "It has been found that VHL deletion (and increased HIF1-α activity) in tubular cells can provide protection against AKI due to IRI and rhabdomyolysis." (PMID 36139884, 2022).
salivary gland adenoid cystic carcinoma (1 paper, 2025). An adenoid cystic carcinoma arising from the salivary gland. "Interestingly, in salivary gland adenoid cystic carcinoma, under hypoxic conditions, HIF-1α binds to the promotor of NID1 to upregulate NID1 expression and increases cancer cell invasion and migration via the PI3K/AKT-EMT pathway." (PMID 40243655, 2025).
salivary gland neoplasm (1 paper, 2023). Tumors of the SALIVARY GLANDS. "Several studies have reported the role of HIF-1α in salivary gland tumors." (PMID 38001981, 2023).
Salivary Gland Pleomorphic Adenoma (1 paper, 2023). A benign, slow-growing tumor composed of cells that demonstrate both epithelial and mesenchymal differentiation. "In this study, we demonstrated for the first time that SM-AP cells, established from salivary gland pleomorphic adenoma, maintain high levels of HIF-1α under hypoxic conditions and show enhanced proliferation by activating their ECM biosynthesis." (PMID 38001981, 2023).
sarcomatoid carcinoma (1 paper, 2025). A malignant epithelial neoplasm characterized by the presence of spindle cells and anaplastic morphologic features. "Y-box binding protein 1 (YB-1) is a conserved protein that induces epithelial-to-mesenchymal transition and further metastasis by binding to HIF-1α and triggering the translation of HIF1A messages, enhancing metastatic capacity in sarcomatoid carcinoma." (PMID 40231252, 2025).
secondary pulmonary hypertension (1 paper, 2016). "Existing in nature as a heterodimer with an α- and β-subunit, two isoforms of HIF (HIF1α and HIF2α) have been shown to influence development of secondary pulmonary hypertension in a chronic hypoxia model of secondary pulmonary hypertension." (PMID 27446973, 2016).
serous carcinomas (1 paper, 2008). "In the 55 patients with stage III, G3 serous carcinoma in this study, the overall survival of patients with tumours that stained strongly for HIF-1α was significantly shorter." (PMID 19014607, 2008). "First we included only poorly differentiated serous carcinomas in the survival analysis of our study and second we observed high HIF-1α expression in almost 50% of the stage I cases (12/25)." (PMID 19014607, 2008). "In the 55 patients with stage III, G3 serous carcinomas, the overall survival of patients with tumours that stained strongly for HIF-1α differed significantly than that of patients with tumours that stained weakly or were negative for HIF-1α (p < 0.05)." (PMID 19014607, 2008).
serous papillary carcinomas (1 paper, 2015). "Expression of ANGPTL4, HER3 and HIF-1α was examined in 35 serous papillary carcinomas." (PMID 26205780, 2015).
T-cell acute lymphoblastic leukemia (1 paper, 2022). Acute lymphoblastic leukemia of T-cell origin. "In patients with T-cell acute lymphoblastic leukemia (T-ALL), HIF-1α is overexpressed, and HIF-1α can promote the activation of Notch1 signaling, increase the expression of cyclin D1, CDK2, p21, MMP2, and MMP9 proteins, thereby leading to cell proliferation, invasion, and resistance." (PMID 35684364, 2022).
thalassemia (1 paper, 2016). An inherited blood disorder characterized by a decreased synthesis of one of the polypeptide chains that form hemoglobin. "Studies showed that Hb E heterozygous individuals have reduced exercise tolerance in accordance with HAPE-S27 and β Thalassemia patients have elevated HIF1α and GLUT1 levels." (PMID 27210110, 2016).
Thrombocytopenia (1 paper, 2022). A reduction in the number of circulating thrombocytes. "The PHD2-deficient mice displayed HIF-2α-induced erythrocytosis, accompanied by excessive RBCs, thrombocytopenia and extramedullary erythropoiesis in the spleen, which effects were all HIF-1α-independent." (PMID 36536448, 2022).
Tinnitus (1 paper, 2024). Tinnitus is an auditory perception that can be described as the experience of sound, in the ear or in the head, in the absence of external acoustic stimulation. "Furthermore, through MR analysis, HIF1A was identified as a potential protective factor, significantly negatively correlated with the risk of tinnitus (OR = 0.78, p = 0.008), while CCND1 showed a positive correlation (OR = 1.22, p = 0.04)." (PMID 39315211, 2024). "However, some studies have suggested that hypoxia may be associated with tinnitus, and HIF1A, as a protein that regulates cellular responses to hypoxia, may influence the occurrence of tinnitus to some extent." (PMID 39315211, 2024). "The action of HIF1A enables patients to protect auditory cells as much as possible under low oxygen conditions, thereby reducing tinnitus." (PMID 39315211, 2024). "Subsequently, through Mendelian randomization analysis, we found that HIF1A and CCND1 are significantly associated with tinnitus disease." (PMID 39315211, 2024). "The results showed significant associations of HIF1A (OR [95 %] = 0.78 [0.65, 0.94], p = 0.008) and CCND1 (OR [95 %] = 1.22 [1.00, 1.49], p = 0.04) with tinnitus in MR analysis IVW results." (PMID 39315211, 2024). "Among them, HIF1A is one of the significantly related targets to tinnitus and is also among the top five key nodes in terms of association degree." (PMID 39315211, 2024). "The results suggest that HIF1A has a potential protective role in the development of tinnitus, while CCND1 has a promoting effect." (PMID 39315211, 2024). "HIF1A may act as a protective target for tinnitus, while CCND1 may promote its occurrence and development." (PMID 39315211, 2024). "However, further research is needed to determine the exact relationship between HIF1A and tinnitus, as well as the potential role of HIF1A in tinnitus treatment." (PMID 39315211, 2024). "MR analysis indicated a significant association between HIF1A and CCND1 with tinnitus." (PMID 39315211, 2024). "Currently, there is also no direct evidence indicating a direct association between HIF1A and tinnitus." (PMID 39315211, 2024). "HIF1A may significantly inhibit the occurrence and development of tinnitus." (PMID 39315211, 2024). "Mendelian randomization analysis revealed that HIF1A (OR [95 % CI] = 0.78 [0.65, 0.94], P = 0.008) and CCND1 (OR [95 % CI] = 1.22 [1.00, 1.49], P = 0.04) exhibited significant results with tinnitus." (PMID 39315211, 2024). "Therefore, we believe that HIF1A may play a key role in the treatment of tinnitus by XCHT." (PMID 39315211, 2024). "HIF1A may play a key role in the treatment of tinnitus by XCHT, which may play a certain protective role in tinnitus patients and may inhibit the occurrence and development of tinnitus." (PMID 39315211, 2024). "Colocalization analysis of HIF1A and CCND1 with tinnitus indicated no shared colocalization for both HIF1A (PH4 = 0.34) and CCND1 (PH4 = 0.02)." (PMID 39315211, 2024).
tongue tumors (1 paper, 2015). "Immunoblotting using lysates derived from these tumors showed that Bnip3 and Hif-1α were marginally elevated in several Sabutoclax-treated tongue tumors." (PMID 26009874, 2015).
tuberous sclerosis (1 paper, 2014). Hereditary disease characterized by seizures, intellectual disability, developmental delay, and skin and ocular lesions. "Level of Hif1α is significantly elevated by hypoxia, which undergoes phosphorylation by ATM to increase REDD1 that activates the tuberous sclerosis complex and results in inhibition of mTORC1 activity." (PMID 25333702, 2014). "Also, we have shown that in the hamartoma syndrome tuberous sclerosis, normoxic elevation of mTOR activity enhances the PTEN tumor suppressor gene expression via upregulation of Hif1α." (PMID 25333702, 2014).
unstable angina (1 paper, 2023). "Reduced HIF-1α expression is also found in heart specimens of diabetic patients with unstable angina." (PMID 37048134, 2023).
uterine disease (1 paper, 2024). "Thus, an increase in the ratio of HIF-1α/VEGF-A is responsible for a more aggressive phenotype of uterine disease." (PMID 39199545, 2024).
vascular malformation (1 paper, 2016). A non-neoplastic disorder that is the result of defects of vascular morphogenesis. "HIF-1α and HIF-2α are up-regulated in vascular malformations in intestinal tissues from GIVM patients, but not in adjacent normal vessels." (PMID 27249651, 2016).
Venous malformation (1 paper, 2023). A vascular malformation resulting from a developmental error of venous tissue composed of dysmorphic channels lined by flattened endothelium and exhibiting slow turnover. "(C–E) Correlation between transforming growth factor A (TGFA) and HIF1A (C), HIF2A (D), and VEGFA (E) mRNA expression levels detected in angiomatosis of soft tissue (AST) and venous malformation (VM) lesions (n=23)." (PMID 37199488, 2023).
venous thromboembolism (1 paper, 2024). Occlusion of the lumen of a vein by a thrombus that has migrated from a distal site via the blood stream. "The expression of the gene encoding VEGF is regulated by HIF-1α, and researchers indicate that there may be a causal relationship between increased VEGF levels and the occurrence of venous thromboembolism." (PMID 39456823, 2024).
ventricular dilatation (1 paper, 2022). "To explore the relationship between ventricular dilatation and HIF-1α expression, we assessed the imaging features of patients in both groups using the Evans index." (PMID 36091021, 2022). "Interestingly, it revealed that the degree of ventriculomegaly was more severe in the low-HIF-1α groups." (PMID 36091021, 2022). "In our study, through the multiplex analysis based on the transcriptome profiles of ACP, we firstly found that HIF-1α expression was significantly upregulated in ACP patients, whereas low HIF-1α scores in the ACP group were correlated with severity of ventriculomegaly and the onset age." (PMID 36091021, 2022).
viral pneumonia (1 paper, 2025). Inflammation of the lung parenchyma that is caused by a viral infection. "However, the roles of HIF1A and HIF2A during viral pneumonia, such as SARS-CoV-2 infections, remain unclear." (PMID 40526427, 2025).
vulvar carcinoma (1 paper, 2013). "In contrast, in the present study, a significantly improved survival of vulvar carcinoma patients with high HIF-1α expression was observed as reported for the squamous cell caricnoma in head and neck region, oral cavity and uterine cervix." (PMID 24165149, 2013). "This confirms the role of HIF-1α for the initiation and the promotion of angiogenesis in vulvar cancer." (PMID 24165149, 2013). "High HIF-1α expression has favorable prognostic impact in vulvar carcinoma patients." (PMID 24165149, 2013). "In vulvar carcinomas, high HIF-1α immunostaining (> 50% tumor cells) in the nucleus was observed in 57 (36%) and low levels (≤ 50% tumor cells) in 101 (64%) cases, whereas high VEGF expression (score ≥ 6) in the cytoplasm was identified in 63 (40%) and low low level (score < 6) in 95 (60%) cases." (PMID 24165149, 2013). "HIF-1α expression in vulvar carcinomas was a statistically independent prognostic factor." (PMID 24165149, 2013).
X-linked hypophosphatemia (1 paper, 2022). X-linked hypophosphatemia (XLH) is a hereditary renal phosphate-wasting disorder characterized by hypophosphatemia, rickets and/or osteomalacia, and diminished growth. "Supporting the notion that there are multiple pathways involved in FGF-23 upregulation beyond phosphate sensing or HIF1α, conditional deletion of HIFα (HIF1α/Osteocalcin (OCN)-Cre) does not reduce FGF-23 levels in the Hyp mice, an animal model of X-linked hypophosphatemia (XLH)." (PMID 36246903, 2022).
Zinc deficiency (1 paper, 2025). A deficiency of the essential metal Zinc; an essential cofactor for many enzymes. "Conversely, zinc deficiency, induced by the zinc chelator TPEN in primary human microvascular endothelial cells, has been shown to upregulate HIF-1α signaling, potentially through enhanced nuclear translocation of HIF-1α and increased secretion of ET-1." (PMID 39995420, 2025).
tumor (7,573 papers, 2002 to 2026). "Studies have shown that the transcriptional response of HIF-1α under hypoxic conditions is driven by epigenetic regulation at low oxygen levels and can promote high-risk tumor characteristics." (PMID 41526224, 2026). "HIF-1α, a central regulator of the cellular hypoxic response, governs the expression of numerous tumor-associated genes." (PMID 41416421, 2026). "Agarose-derived spheroids exhibited time-dependent growth, positive Ki-67 staining, and increased HIF-1α expression under 3D conditions, indicating the establishment of hypoxia-associated tumor-like microenvironments." (PMID 42196063, 2026). "A meta-analysis of 25 studies showed positive associations of HIF1A protein overexpression with tumor grade, lymph node invasion, and invasion of the cancer-affected cells into the myometrium." (PMID 39888575, 2026). "Rapid tumour growth and aberrant vascular architecture cause hypoxia (which is the stabilization of hypoxia inducible factors e.g. HIF-1α and HIF-2α)." (PMID 41476776, 2026). "Hypoxia‐inducible factor‐1 alpha (HIF‐1a) driven hypoxia is a common phenotypic feature that underlies the increased glycolysis and aggressive tumor phenotype." (PMID 41521160, 2026). "HIF-1α mediates hypoxia-induced transcription and is implicated in tumor growth, metastasis, and treatment resistance." (PMID 41438580, 2026). "In this hypoxic state, macrophages are also oxygen-deprived, and HIF-1α stimulates tumor-associated macrophages (TAMs) to produce various factors, such as VEGF, IL-1β, TGF-β1, tumor necrosis factor (TNF)-α, basic fibroblast growth factor (bFGF), and IL-10." (PMID 40034694, 2025). "In PCa, a high expression of HIF1α is frequently associated with tumor hypoxia, radiotherapy resistance, and poor prognosis." (PMID 40430845, 2025). "The data indicate that the high expression of HIF-1α was associated with tumor proliferating and poor prognosis." (PMID 40011266, 2025). "In many cancers, VHL gene mutations or deletions result in loss of VHL function, leading to HIF-1α accumulation and tumor progression." (PMID 41446875, 2025). "In particular, HIF1α was shown to promote tumor-associated vascular remodeling by up-regulating the expression of target genes involved in angiogenesis, including VEGFA and matrix metalloproteinases (MMP)." (PMID 39953610, 2025). "HIF-1α, a transcription factor stabilized under hypoxia and linked to angiogenesis and tumour survival, was analyzed to assess treatment-induced hypoxia from vascular disruption by MB + FUS + XRT." (PMID 41148833, 2025). "Leptin promotes tumor angiogenesis by upregulating HIF-1α and VEGF, Conversely, adiponectin deficiency leads to reduced expression of anti-angiogenic factors (e.g., thrombospondin-1), further exacerbating vascular abnormalities." (PMID 41164182, 2025). "These processes are regulated by oncogenic alterations such as EGFR amplification, PTEN loss, and HIF-1α stabilization, which allow tumor cells to thrive in hypoxic and nutrient-poor environments." (PMID 41450919, 2025). "This reduction is associated with decreased infiltration of lymphocytes into the tumor microenvironment, increased expression of hypoxia-inducible factor-1α (HIF-1α; encoded by HIF1A), and a poorer prognosis regarding distant metastasis-free survival." (PMID 41550427, 2025). "Nonetheless, the consistent association of HIF-1α overexpression with higher stage and deeper invasion across multiple studies suggests it is linked to aggressive tumor behavior." (PMID 40546546, 2025). "In GBM, a higher WWOX/HIF1A ratio is linked to better patient outcomes, reflecting the tumour’s biological behaviour and signalling pathways." (PMID 41007296, 2025). "Simultaneously, lactate stabilizes HIF-1α in myeloid cells, driving polarization toward M2-like tumor-associated macrophages that further suppress antitumor immunity." (PMID 40552288, 2025).